MCL1 (MCL1 apoptosis regulator, BCL2 family member)
Diseases named in the same sentence as MCL1 in open-access papers (continued):
Sharing a sentence is not in itself a finding about the gene and the disease.
tumor (continued). "However, in end-stage tumors, Mcl-1 expression had recovered, showing its requirement for tumor development." (PMID 35053443, 2022). "Consistent with the presumed synergistic effect on mitotic exit, APC/C-inhibition alone or combined with a taxane can lead to strong mitotic cell death in certain tumor cells, but in others with high expression of the anti-apoptotic regulator Mcl-1, cell death is induced in interphase." (PMID 35832196, 2022). "Interestingly, TRAF4 and MCL-1 levels exhibited significantly higher levels in relapsed tumor tissues than in primary tumor tissues, and the positive correlation between TRAF4 and MCL-1 was also observed in the relapsed tumors." (PMID 36535926, 2022). "Analyzing the other ten samples without sequencing data, another sample fulfilled FISH criteria for MCL1 amplification (patient 10) with a MCL1/1p12 ratio of 2.6 (average gene copy number: 6.7, tumor cells with ≥ 4.0, ≥ 5.0, and ≥ 15.0 gene signals were 88%, 82%, and 0%, respectively)." (PMID 35668118, 2022). "However, there was also a high probability that MCL1 was co-expressed to medium/high levels in CRC tumor samples with medium/high expression of Bcl-xL and this was more common in stages III−IV than stages I−II." (PMID 35042842, 2022). "The dysregulation of Mcl-1 may occur at multiple levels so as to maintain its sustained elevated levels to ensure tumor cell survival." (PMID 36045907, 2022). "In addition, radotinib repressed expression of the activity and expression of STAT3, and its downstream proteins including Bcl-xL, Mcl-1, c-Myc, cyclin D1, and cyclin D3 in IM-9 cells isolated from the tumor tissue." (PMID 35503759, 2022). "We also observed the size of tumor in mice was closely correlated with MCL-1 expression." (PMID 35136016, 2022). "Thus, each threshold delimited two areas: “low and high” tumor response for Bim (45%), Mcl-1 (25%), and P-ERK (85%), respectively." (PMID 36303844, 2022). "Analyzing the clinical effects of chemotherapy on CAF expressed MCL-1 may thus help predict tumor response." (PMID 36104324, 2022). "Mcl-1 inhibits cell death by binding to pro-apoptotic Bcl-2 family members to suppress mitochondrial outer membrane permeabilization and caspase activation, through which tumor cells evade the fate of death." (PMID 35301297, 2022). "When CSC is exposed to chemotherapeutic agents in vivo, some special regulatory mechanisms will be activated; pi3-K, MAPK and other pathways will be cascade-activated, and then the anti-apoptotic protein myeloid cell leukemia-1 (McL-1) will increase to inhibit the apoptosis of tumor cells." (PMID 36172536, 2022). "When it comes to the PI3K/AKT pathway, the dual PI3K and HDAC inhibitor CUDC-907 not only overcomes venetoclax resistance by upregulating BIM and downregulating MCL-1 but also synergizes with venetoclax to further promote tumor cell apoptosis because of its DNA damage-mediating effects in AML." (PMID 36313732, 2022). "As one of the most important Bcl-2 family members, Mcl-1 plays critical roles in suppressing apoptosis in tumor cells, which however may not affect the survival of SnCs, as inhibition of Mcl-1 with its specific inhibitor did not cause cell death in SnCs." (PMID 35252191, 2022). "Thus, the complex multimodal upregulation of prosurvival Mcl-1 ensures tumor cell viability and thereby contributes to tumorigenesis." (PMID 36045907, 2022). "However, in vivo aberration/upregulation of MCL-1 in TNBC carcinoma tissues positively links with extraordinary tumor proliferation and poor patient persistence." (PMID 36267139, 2022). "The exact role that MCL1 plays in tumour initiation in LAC cells remains unclear, and deserves further studies to clarify." (PMID 35794816, 2022). "Formononetin inhibited tumor growth by inhibiting the EGFR-Akt-Mcl-1 axis in NSCLC." (PMID 36523419, 2022).
tumor (continued). "For the TCTP-mediated anti-apoptotic response to CTLs, we noted an increase in anti-apoptotic protein MCL-1, a signature molecule rendering tumor cells resistant to CTL-induced killing in previous studies, in CT26 P3 cells as well as CT26 TCTP cells, relative to P0 or CT26-no cells, respectively." (PMID 35440620, 2022). "One implication is that the therapeutic potential of BH3 mimetics inhibiting MCL-1 may be preclinically overlooked if reductive models using only tumor cells are used." (PMID 36104324, 2022). "Indeed, targeting of MCL-1 has been shown to sensitize cells and effectively inhibit tumor growth in vitro and in vivo when administered in combination with BCL-2/BCL-XL inhibitors." (PMID 35349392, 2022). "MCL-1 overexpression is involved in delaying various stimuli that induce apoptosis and might protect tumour cells from PDT-induced death." (PMID 36365208, 2022). "Therefore, by using the targeting effect of CP7 to deliver Mcl-1 siRNA to A549 cells, the overexpressed Mcl-1 will be inhibited, followed by the promotion of tumor cell apoptosis and the inhibition of tumor growth." (PMID 35955516, 2022). "However, data derived in pre-clinical models of solid tumors emphasize a broader function for Bcl-xL and/or MCL1 in the maintenance of tumor cell survival." (PMID 35042842, 2022). "A yet unexplored functional role of nuclear MCL1 could be to act as a chaperon of pro-oncogenic proteins into the nucleus that promotes tumor progression and chemoresistance." (PMID 35042842, 2022). "Thus, regardless of senescence heterogeneity, our analysis identified Mcl-1 as a ubiquitous target to effectively remove senescent tumor cells." (PMID 35449130, 2022). "The derivatives showing potent anti‐BMI1/MCL1 effect, such as compounds #43–45, were selected for further in vivo anti‐tumour test, in which compound #44 (named as BI‐44 in this study) showed significant anti‐tumour growth effect." (PMID 35794816, 2022). "Therefore, overall MCL1 (indicated as ‘MCL1’, scoring the total intensity of MCL1 in tumour cells) and nuclear MCL1 (indicated as ‘nMCL1’, scoring the intensity of MCL1 only in nucleus) were independently scored." (PMID 35794816, 2022). "Indeed, GBM displayed an obligate requirement for MCL-1 expression in both tumour development and maintenance." (PMID 35473984, 2022). "Notably, the current study revealed that MCL-1 was overexpressed in tumor tissues, particularly in relapsed tumor samples of patients with OSCC." (PMID 36535926, 2022). "The therapeutic window for exploiting the effects of MCL-1 targeting on a myofibroblastic tumor stroma described here may thus be narrow, unless specific tumor delivery strategies intervene." (PMID 36104324, 2022). "For example, in BC, BAG3 up-regulates the expression levels of Bcl-2 and Bcl-xL by targeting HSP70/Mcl-1 signaling pathway and suppresses the chemoresistance of tumor cells, indicating that BAG3 may be a potential target for treating BC." (PMID 36228497, 2022). "Immunoblotting of tumor lysates showed an obvious reduction in MCL-1 levels in the MCL-1 knockdown group, but little effect on AKT/ HIF-1α pathway molecules while compared with vehicle treatment group, suggesting that MCL-1 acts as a downstream factor in the AKT/ HIF-1α signaling pathway." (PMID 35136016, 2022). "Importantly, combinatorial therapy caused significant reduction in tumor burden compared with VEN or AZD5991 single agent cohorts, indicating that MCL-1 inhibition with AZD5991 restored VEN sensitivity in MOLM-13 NRAS-G12D CLDX." (PMID 35185150, 2022). "Based on our observations, criteria for FISH positivity in PB could be defined (MCL1 amplification: MCL1/1p12 ratio ≥ 2.0 and/or average gene MCL1 count per tumor cell ≥ 5.0)." (PMID 35668118, 2022). "The results showed that TRAF4 knockout or suppression of MCL-1 with S63845 combined with radiotherapy could significantly inhibit tumor growth." (PMID 36535926, 2022).
tumor (continued). "Additionally, immunohistochemistry (IHC) of matched tumour cores and predominantly non-tumorous margins of three patients confirmed increased BCL-xL and MCL-1 expression within the tumour cores compared to the margins." (PMID 35473984, 2022). "Moreover, TRAF4 was positively correlated with MCL-1 in primary and in radiotherapy-treated, relapsed tumor tissues." (PMID 36535926, 2022). "MCL1, a pro-survival and pro-proliferative factor, plays a critical role in many tumor types." (PMID 35444548, 2022). "There was a positive correlation between TRAF4 and MCL-1 in primary and relapsed tumor samples." (PMID 36535926, 2022). "In contrast, knocking down Mcl-1 by small interfering RNAs (siRNAs) potentiated the apoptosis of KYSE30 cells induced by SNS-032, as evidence by higher protein levels of PARP cleavage and larger percentage of dead cells in Mcl-1-depleted cells than those of tumor cells transfected with Mock siRNA." (PMID 34741018, 2021). "Moreover, siRNA-mediated STAT3 inhibition reduced the total protein levels of tumor-promoting genes Mcl1, Cyclin D1, VEGF, and Bcl-XL, suggesting that STAT3 is required for proliferation and survival in Olaparib-resistant cells." (PMID 34956861, 2021). "In addition, NAP1L1 knockdown attenuates p65 binding to the antiapoptotic Mcl-1 gene promoter and reduces its expression, which finally induced cell apoptosis in tumor cells." (PMID 34774047, 2021). "Such side effects could be avoided by tumor cell-specific inhibition of Mcl-1, for example by RNA interference-mediated silencing of Mcl-1." (PMID 34028599, 2021). "Indeed, when c-MYC activation/overexpression was coupled to overexpression of the anti-apoptotic gene Mcl-1, the pro-apoptotic function of TGFβ1 was bypassed, ultimately resulting in tumor formation." (PMID 33608500, 2021). "MCL1 was found to be highly enriched in bio-miR-320b probes in human granulosa-like tumor cells." (PMID 34413875, 2021). "In addition to its well-recognized role as an inhibitor of apoptosis, MCL1 has also been shown to have an effect on the migratory and invasive capacity of tumor cells." (PMID 34469478, 2021). "We delineate their mechanism of action, highlighting Mcl-1 as a key target of their anti-tumour activity and therefore provide further impetus for the future utilisation of these inhibitors as a novel treatment option for GBM patients in both the primary and recurrent setting." (PMID 34344865, 2021). "In addition to its tyrosine kinase inhibitory effect, sorafenib was described to induce cell death through the inhibition of elF4E phosphorylation and Mcl-1 expression in tumor cells." (PMID 34639131, 2021). "Therefore, these evidences firstly revealed that a novel circPVT1/miR-339-3p/MCL-1 axis regulated tumor process in GBC." (PMID 34312371, 2021). "Subsequently, Mcl-1 was found to be an essential pro-survival molecule in multiple tumor types, warranting the recent advancements of Mcl-1 specific BH3-mimetics in clinical trials, including AMG-176 (Amgen), S64315 (Servier), and AZD5991 (AstraZeneca) [reviewed in detail elsewhere]." (PMID 34336857, 2021). "To determine whether emetine suppressed the growth of PC9-ErlR tumors through the inhibition of HSF1 in vivo, we measured the protein levels of HSF1, EGFR, HSP27, and MCL1 in tumor tissues of emetine- and control-treated mice." (PMID 34203709, 2021). "RNASET2 upregulation, together with the inhibition of phAKT, phmTOR, and Mcl-1 might be part of an “editing” process that leads to the elimination of pro-tumor immature DCs." (PMID 34299186, 2021). "It is related to tumor progression, metastasis, drug resistance, and promotes apoptosis at mitochondria by activating proteins Bax and Bak and by inhibiting the anti-apoptotic proteins Bcl-XL, Bcl-2, and Mcl-1." (PMID 34955827, 2021).
tumor (continued). "In addition, we revealed that a novel circPVT1/miR-339-3p/MCL-1 axis promoted tumor progression in GBC." (PMID 34312371, 2021). "Identified as most frequently mutated housekeeping gene in HCC tissue, mutant ACTB 3′UTR acted to inhibit miR-29a by direct interaction, whereby miR-29a target gene MCL1 apoptosis regulator, BCL2 family member (MCL1) was up-regulated to bolster tumor progression." (PMID 33803804, 2021). "As a potent inducer of DNA damage in targeted tumor cells, it is anticipated that 225Ac‐lintuzumab may mediate effective down‐modulation of MCL‐1 leading to a sensitization of AML cells to venetoclax irrespective of inherent resistance to the BCL‐2 inhibitor." (PMID 33347715, 2021). "Importantly, we found that the anti-tumour functions achieved by MCL-1 deletion or inhibition were completely dependent on pro-apoptotic BAX/BAK." (PMID 33785871, 2021). "Additionally, the protein expression levels of resistance markers (p-gp and MCL-1) and Wnt/β-catenin pathway markers (β-catenin and c-Myc) in OS tumor tissues were significantly decreased by hsa_circ_0004674 knockdown and DXR treatment." (PMID 34407841, 2021). "Furthermore, to investigate the relationship among BMI and leptin levels and OBR, pSTAT3, CEBPD, and MCL1 expression, patient serum and tumor specimens were evaluated by ELISA and IHC, respectively." (PMID 34156978, 2021). "In this study, we transfected OE-NC, OE-circMTO1, OE-circMTO1 + si-NC, and OE-circMTO1 + si-MCL1 into human granulosa-like tumor cells, we found that the downregulation of MCL1 reversed the effects of circMTO1 on human granulosa-like tumor cell proliferation and apoptosis." (PMID 34413875, 2021). "Therefore, the antitumor activity of the combination of Dox and Mcl-1 siRNA was evaluated in the MCF-7 multicellular tumor spheroid model to simulate the tumor environment in vivo better while circumventing the usage of laboratory animals." (PMID 33919902, 2021). "Of relevance, tumor microenvironment may determine an additional support in maintaining the expression of Notch2 and Mcl-1, especially at the lymph node level." (PMID 35070982, 2021). "In addition, IL6 upregulates Mcl-1 (an apoptosis inhibitor) enhancing tumour cells survival by increasing expression of STAT3." (PMID 33579265, 2021). "This difference could be attributed to the downregulation of their potential targets (e.g., BIRC2 baculoviral IAP repeat containing 2 (cIAP1) and MCL1 apoptosis regulator (MCL1)), important in tumor cell survival following TKI treatment." (PMID 34830398, 2021). "Pharmacological inhibition of PP2A with small molecule compound LB-100 decreased MCL1 protein level, caused more apoptosis in nab-PTX resistant ESCC cell lines than in the parental cells in vitro, and significantly inhibited the tumor growth of nab-PTX resistant xenografts in vivo." (PMID 34638252, 2021). "Having previously demonstrated an essential genetic requirement for MCL-1 in tumour development in the MMTV-PyMT mammary model we wanted to mimic therapeutic targeting of MCL-1 in an adjuvant setting by determining the impact of Mcl1 deletion in established tumours." (PMID 33785871, 2021). "This study demonstrated that A549 expressed MCL1 to resist CD8+ T cell-mediated tumor apoptosis." (PMID 34685495, 2021). "Notably, FBW7 has been classified as a tumor suppressor that induces degradation of several proto-oncogenes such as c-Myc, cyclin E, and myeloid cell leukemia-1 (MCL-1)." (PMID 33471866, 2021). "Furthermore, as a downstream target gene of RNA Pol II, MCL1 is closely related the survival and maintenance of tumor cells." (PMID 34372855, 2021). "Mcl-1 is an antiapoptotic member of the Bcl-2 family that has been found to play a critical role in the survival of various types of normal cells and resistance of tumor cells to various anticancer drugs." (PMID 35008442, 2021). "We found a novel SNAI2/circMTO1/miR-320b/MCL1 axis in human granulosa-like tumor cell progression." (PMID 34413875, 2021).
tumor (continued). "Circ_0004674 knockdown remarkably suppressed OS cell chemoresistance, proliferation, migration, invasion, OS tumor growth, and enhanced cell cycle arrest and apoptosis in vitro and in vivo through control the expression of the antiapoptotic protein MCL1, a member of the Bcl-2 gene family." (PMID 34689155, 2021). "These therapies may target MCL-1 more selectively in tumor cells, and could help circumvent the toxicity expected with direct MCL-1 inhibition in combination with BCL-XL/BCL-2 targeting." (PMID 35008216, 2021). "Importantly, MCL-1 inhibitors markedly suppress colony formation on soft agar and tumor growth of KSHV+PEL/BCBL-1 in a xenograft mouse model." (PMID 33471866, 2021). "Interestingly, inactivation of just one allele of Mcl1 in these mice (denoted HET), at a time when palpable tumours had already established, was sufficient to restrict tumour growth and significantly extend survival." (PMID 33785871, 2021). "Moreover, MDA-MB-468 TNBC were highly susceptible to chemical MCL1 inhibition or genetic ablation and tumours forming in the MMTV-PyMT mouse model of BC showed clear MCL1 dependence." (PMID 34903710, 2021). "Gene knockdown studies proved that amplified MCL-1 enabled the survival of these tumours." (PMID 34581776, 2021). "Instead, it is MCL-1 which appears to be the key factor driving the sustained growth of Eμ-MYC lymphoma and even the loss of a single allele was enough to lead to complete regression in 20% of tumours." (PMID 33799592, 2021). "Given the lack of recurrent MCL-1 mutations, tumor cells require alternative mechanisms to overcome this vulnerability in order to sustain MCL-1 activity." (PMID 33308268, 2020). "Furthermore, knockdown of Mcl-1 has been demonstrated to decrease cell survival and reverse drug-resistance of tumor cells." (PMID 32212793, 2020). "Collectively, the data suggest that the absence of HTATIP2 expression promotes an aggressive tumor phenotype by enhancing the HIF2α-regulated β-catenin/c-Myc/MCL-1 signaling, increasing the susceptibility of tumors to sorafenib-activated EMT process, and improving tumor metabolic plasticity." (PMID 32545251, 2020). "Those proteins included HIF1α, HIF2α and their target genes c-Myc and β-catenin, as well as MXI1 and MCL-1 that are closely associated with c-Myc, EMT markers and effectors of the Akt signaling pathway that are potentially associated with tumor response to sorafenib treatment." (PMID 32545251, 2020). "Moreover, combined inhibition of glycolysis and OXPHOS indirectly affects MCL-1 expression and thus induces cell death in tumor cells." (PMID 33308268, 2020). "Concordantly, adding drugs that down-regulate Mcl-1 sensitized tumor cells to ABT-737." (PMID 32212793, 2020). "Previous studies found a close relationship between Mcl-1 and tumor chemotherapy resistance." (PMID 32932732, 2020). "As a consequence, the BCL-xL/MCL-1 ratio was significantly improved in the HCC tumor group." (PMID 32024199, 2020). "With the clinical development and success of the BCL-2 inhibitor venetoclax in mind, MCL-1 inhibitors may become the next novel class of anti-tumor agents with considerable potential across different malignancies." (PMID 33308268, 2020). "However, a detailed understanding about the tumor and tissue type specific implications of MCL-1 are a prerequisite for the optimal (i.e., precision medicine guided) use of this novel drug class." (PMID 33308268, 2020). "Previous studies demonstrated that S63845 could kill effectively Mcl-1 dependent tumor cells in a BAX-BAK-dependent fashion." (PMID 33362794, 2020). "MCL-1 has been shown to play a significant role in promoting cell survival in AML cell lines, and its overexpression in tumor cells may be associated with resistance to radiotherapy, chemotherapy, and BH3-mimetics targeting BCL-2/BCL-XL." (PMID 33251145, 2020).